SCYGR8 (small cysteine and glycine repeat containing 8)
Description:
In the hair cortex, hair keratin intermediate filaments are embedded in an interfilamentous matrix, consisting of hair keratin-associated proteins (KRTAP), which are essential for the formation of a rigid and resistant hair shaft through their extensive disulfide bond cross-linking with abundant cysteine residues of hair keratins. The matrix proteins include the high-sulfur and high-glycine-tyrosine keratins.
Synonyms: KRTAP28-8
Gene: Protein-coding gene on chromosome 2 (227,745,894 to 227,746,220, forward strand). Ensembl gene ENSG00000284635.
Homologues: Orthologues: chimpanzee SCYGR8 (96% identical), pig SCYGR8 (81% identical), dog SCYGR8 (78% identical).